KL (klotho)
Diseases named in the same sentence as KL in open-access papers (continued):
Sharing a sentence is not in itself a finding about the gene and the disease.
cancer (continued). "KL is a potent regulator of IGF-1R and Wnt/β-catenin signaling, and these pathways are highly relevant for the cancer microenvironment." (PMID 33520985, 2020). "KL expression is critical for adipose tissue homeostasis but is altered in DDLPS, probably by epigenetic regulations as in several other cancers." (PMID 30441794, 2018). "Furthermore, cancer survivors exhibited a sustained linear decrease in Klotho levels with increasing PIV, while non-cancer survivors demonstrated a U-shaped relationship." (PMID 40519908, 2025). "This provides insight into the knowledge of nonlinearity relationship between serum Klotho, a longevity hormone, and survival outcomes in cancer populations." (PMID 40696614, 2025). "There was a significant difference in the frequency of lung metastasis between the A549 and A549/KL cells; no lung metastasis occurred in mice that received A549/KL cells, confirming that KL expression suppressed cancer cell metastasis." (PMID 38267588, 2024). "Klotho blocked TGF-β1 and suppressed renal fibrosis and cancer metastasis in mice." (PMID 39272986, 2024). "The study examines the relationship between relatively stable and not transient variations in Klotho levels and distant cancer." (PMID 37752937, 2023). "The research suggested that once mice lacked the Klotho gene, there would be functional disorders similar to human atherosclerosis, cancer and osteoporosis." (PMID 35841322, 2023). "As benign mammary tumors are known to gradually progress into malignant tumors in dogs, it is not unusual for klotho expression to decrease as malignancy increases." (PMID 35666743, 2022). "For the malignant tumor group, grade, Ki-67 level, and the presence of metastasis during the follow-up period were significantly correlated with the absence of klotho expression." (PMID 35666743, 2022). "Altogether, this strategy can serve not only to maintain and improve the quality of life in the elderly, but also to decrease the economic cost overruns to health care systems derived from pathologies that imply low levels of S-Klotho (e.g., neurological disorders, CKD, and cancer)." (PMID 35566540, 2022). "Among the samples, 11% (3/28) of benign tumors and 26% (7/27) of malignant tumors showed negative klotho expression." (PMID 35666743, 2022). "In normal mammary glands, all tissues showed positive klotho expression, whereas, in benign and malignant tumors, 11% and 26% showed negative expression, respectively." (PMID 35666743, 2022). "Non-conditional KLOTHO knockout mice die at around 8–9 weeks of age, hence, they cannot serve as models for cancer development." (PMID 34944918, 2021). "Soluble klotho may antagonize Wnt and transforming growth factor-β (TGF-β) signaling thus preventing tissue fibrosis and cancer metastasis." (PMID 28912623, 2017). "Further, klotho could modulate the repair activity of the DNA through regulation of ERCC1, then change the resistance of the cancer cells." (PMID 23437382, 2013). "Notably, cancer survivors exhibit a distinct pattern in the PIV-Klotho relationship compared to non-cancer participants." (PMID 40519908, 2025). "The clinical implications of our study are significant as they suggest that Klotho may not universally serve as an effective biomarker or therapeutic target across all cancer types." (PMID 41261673, 2025). "No study has prospectively assessed serum Klotho and survival outcomes in cancer populations." (PMID 40696614, 2025). "Moreover, Klotho inhibits autophagy, inhibits glycolysis (via hexokinase/HK, phosphofructokinase 1/PFK1, PK M2, and PDK1), fatty acid synthesis, and purine metabolism—some specific to cancer cell effects—making it a promising drug target candidate." (PMID 37109525, 2023). "Since Klotho itself is a circulating hormone and the higher level of serum Klotho had a strong negative effect on hormone‐related cancers, we speculated that serum Klotho might play this role by influencing the level of sexual steroid hormones." (PMID 35841322, 2023).
cancer (continued). "Clinical survival analysis of various cancer types, however, has not demonstrated unequivocal involvement of Klotho in the carcinogenic process and it is still unclear whether the inconsistent role of Klotho in carcinogenesis is dependent on epigenetic variability or other factors." (PMID 28870231, 2017). "miR-15b may contribute to reduced KL expression in CRC because higher miR-15b levels in CRC patients compared to healthy subjects, those with metastasis than without, and those with cancer recurrence than without are described." (PMID 33520985, 2020).
neurodegenerative disease (25 papers, 2015 to 2026). A disorder of the central nervous system characterized by gradual and progressive loss of neural tissue and neurologic function. "As individuals age, levels of s-Klotho decline, which has been associated with cognitive deficits and an increased risk of neurodegenerative diseases such as AD [1373]." (PMID 40407975, 2025). "Given its wide range of protective effects, s-Klotho has emerged as a potential therapeutic target for combating both vascular and neurodegenerative diseases associated with aging." (PMID 40407975, 2025). "Klotho deficiency has been linked to numerous inflammatory and degenerative diseases involving the kidneys, cardiovascular system, brain and other organs." (PMID 39272986, 2024). "Klotho is reported to be involved in numerous ageing-associated pathologies, such as cardiovascular disease, chronic kidney disease, cancer, and neurodegenerative disease." (PMID 35327507, 2022). "Despite the close association between Klotho and neurodegenerative diseases, such as AD, the underlying mechanism by which Klotho contributes to AD remains poorly understood." (PMID 35327507, 2022). "Reduced expression of the Klotho gene or α-Klotho protein level are associated with a shorter lifespan and risk of neurodegenerative diseases, as well as accelerated aging and premature morbidity and mortality." (PMID 34721095, 2021). "Klotho was initially linked to neurodegenerative diseases in studies of AD." (PMID 36552155, 2022). "In addition, the potential for klotho together with other known treatments to attenuate age associated pathologies and as a biomarker for certain diseases including renal, cardiovascular and neurodegenerative diseases has been suggested." (PMID 38352710, 2024). "In the brain, Klotho exhibits neuroprotective effects, promoting cognitive function and protecting against neurodegenerative diseases." (PMID 39239870, 2024). "Klotho has been shown to confer cognitive resilience in healthy aging and neurodegenerative disease." (PMID 36552155, 2022). "This is one likely mechanism by which Klotho exerts its antiaging action, and protection against degenerative diseases." (PMID 35903083, 2022). "The anti-aging protein Klotho has been reported to negate oxidative stress and inflammation when it is overexpressed; for example, in neurodegenerative diseases, Klotho possesses anti-inflammatory properties." (PMID 33072166, 2020). "Noticeably, a growing body of evidence asserts the therapeutic potential of Klotho in treating neurodegenerative diseases." (PMID 32257625, 2020). "Klotho, a pleiotropic protein initially identified for its role in kidney function, has garnered significant attention for its neuroprotective properties in various neurodegenerative diseases." (PMID 41983942, 2026). "It is thus conceivable, but not yet certain, that both RAAS inhibitors and statins can enhance Klotho expression in the human brain, and this might protect against neurodegenerative diseases." (PMID 35903083, 2022). "Finally, as a regulator of remyelination in the white matter, Klotho can become a new therapeutic substance for MS and other demyelinating and neurodegenerative diseases." (PMID 30062646, 2018). "Why is Klotho of particular interest for neurodegenerative diseases?" (PMID 30062646, 2018). "Given the significance of TREM2 variants in neurodegenerative disease and impaired microglial functioning, our findings indicate that the interaction between NMES and KLOTHO deficiency may be explained by a dysfunction in signaling processes necessary for immune recovery." (PMID 40869172, 2025). "Could some of these drugs ameliorate neurodegenerative diseases by enhancing Klotho?" (PMID 35903083, 2022). "Thus, releasable Klotho present a very interesting humoral factor that could be helpful to find new means against neurodegenerative diseases." (PMID 31001090, 2019). "Klotho enhancers may be a new therapeutic approach in the treatment of neurodegenerative diseases." (PMID 29088855, 2017).
neurodegenerative disease (continued). "Increasing Klotho levels could provide an additional preventive and therapeutic effect by enhancing glymphatic function and reducing AQP4 mislocalization—two conditions associated with aging and neurodegenerative diseases—possibly through the modulation of AQP4ex function." (PMID 40691670, 2025). "The authors concluded the enhancement of s-Klotho and α-processing of APP both contributed to the amelioration of the neurodegenerative disease." (PMID 35903083, 2022). "Klotho overexpression inhibits the NLRP3/caspase signaling pathways and enhances cognition in animal models of neurodegenerative disease." (PMID 36552155, 2022). "These antidiabetic drugs possibly ameliorate neurodegenerative disease in some patients, but a potential contribution of Klotho, to our knowledge, has not been examined." (PMID 35903083, 2022). "In the case of neurodegenerative diseases it is relevant that some drugs, including some traditional medicines, cross the BBB and might increase Klotho in the brain." (PMID 35903083, 2022).
metabolic disease (16 papers, 2015 to 2025). A congenital disorder (due to inherited enzyme abnormality) or acquired (due to failure of a metabolically important organ) disorder resulting from an abnormal metabolic process. "This dual role in metabolic regulation, antioxidation, and anti-aging renders Klotho an important potential target for the treatment of metabolic diseases and the delay of aging." (PMID 40427517, 2025). "Concurrently, pro-aging and pro-inflammatory signaling cascades are suppressed, thereby establishing the molecular foundation for Klotho’s anti-aging effects, its mitigation of metabolic diseases, and its prevention of tissue fibrosis." (PMID 40427517, 2025). "Ordered logistic regression is employed to evaluate the relationship between Klotho and the combined burden and accumulated risk of CVD complicated with metabolic disorders." (PMID 40369033, 2025). "Elevated FGF-23 levels lower Klotho expression, so its suppressing effect on klotho production can induce vascular and metabolic disorders." (PMID 36362179, 2022). "Klotho mRNA expression in rat kidney is down regulated in various animal models of vascular and metabolic diseases such as hypertension, hyperlipidemia, renal failure, and inflammatory stress." (PMID 30483154, 2018). "It regulates glucose and lipid metabolism, bile acid synthesis and energy balance by binding to receptors such as FGFR1 c, and shows potential application value in the treatment of metabolic diseases.However, γ-Klotho is mainly expressed in the reproductive system and some tumor tissues." (PMID 41438297, 2025). "Interestingly, the calpain 1 inhibitor BD-410 significantly upregulates Klotho protein which ameliorates aging-induced syndromes and remedies calcium and phosphorus metabolism disorders." (PMID 35155498, 2022). "However, the present results contrast with the decreased renal gene expression of Klotho observed in various animal models of vascular and metabolic diseases." (PMID 30483154, 2018). "Thus, the study of KL protein is meaningful to the aging, apoptosis, angiocardiopathy, and metabolic diseases." (PMID 26379754, 2015). "Furthermore, although mediation analysis has offered insights into the intricate interplay among Klotho, CVD, and metabolic disorders, the causal pathways that underlie these relationships remain speculative." (PMID 40369033, 2025). "Notably, KL treatment could improve β-cell function and glucose homeostasis, suggesting it would be effective in metabolic diseases." (PMID 40018267, 2025). "In conclusion, to our knowledge, this is the first study demonstrating that smoking simultaneously increases two Klotho-related molecules; sαKl, capable of affecting anti-inflammatory cytokine network and FGF-21, a possible indicator of progressing metabolic disorder in men." (PMID 26382974, 2015).
heart disease (13 papers, 2019 to 2025). "The klotho protein, originally associated with aging and longevity, is emerging as a potential biomarker for heart disease due to its involvement in critical cellular processes of the cardiovascular system." (PMID 38792942, 2024). "Klotho is associated with various physiological processes in the body, including its potential role in heart diseases." (PMID 38792942, 2024). "The klotho protein has been linked to the regulation of various cellular processes, including endothelial function, oxidative stress, inflammation and fibrosis, all of which are critical factors in the development and progression of heart diseases." (PMID 38792942, 2024). "Therefore, the design of new strategies directed to increase Klotho levels should be considered as a strategy to reduce morbidity and mortality associated with kidney and heart diseases." (PMID 32188018, 2020). "In line with our research, these studies all observed the elevation phenomenon of Klotho expression in heart disease." (PMID 39330350, 2024). "The current study shows that both Klotho and FGF23 are independently altered and associated with concentric hypertrophy in CKD patients, thus being suitable as indicators of cardiac disease in this population." (PMID 30934737, 2019). "The main objective was to ascertain the potential use of plasmatic Klotho and FGF23 as markers for CKD-associated cardiac disease and mortality." (PMID 30934737, 2019). "Decreased levels of klotho potentially contribute to the development of fibrotic heart disease." (PMID 38792942, 2024). "In veterinary medicine, the assessment of Klotho in heart disease could be of interest for future studies, as it shows promising properties and potential applications in disease therapy and prevention." (PMID 38787156, 2024). "In recent years, the role of Klotho in heart disease has garnered attention." (PMID 39330350, 2024). "Klotho administration also suppressed the expression of Angiotensin-II receptor type I showing that Klotho might be considered as an antihypertrophic factor useful in heart diseases." (PMID 32188018, 2020). "In line with the recent work of Drew and collaborators, the present work used a pool of 107 CKD patients to ascertain the potential use of plasmatic Klotho, FGF23 or both, as markers for CKD-associated cardiac disease and to discuss their eventual use as therapeutic targets in CKD." (PMID 30934737, 2019). "Furthermore, when assessing Klotho in heart diseases, it must be considered whether the heart disease is present alone or in conjunction with other diseases." (PMID 38787156, 2024). "Thus, restoring Klotho expression could be an alternative treatment option for CKD patients with heart disease." (PMID 32464602, 2020). "We did not consider Klotho as a biomarker for diagnosing heart disease in this context." (PMID 38787156, 2024).
bone disorder (11 papers, 2013 to 2026). "Second, klotho is a major regulator of calcium and phosphorus homeostasis by preventing cardiovascular calcification associated with CKD mineral and bone disorder." (PMID 39281418, 2024). "Klotho modulates the calcium and mineral homeostasis and the triad composed by α-Klotho, fibroblast growth factor-23, and its receptor is involved in the pathogenesis of mineral and bone disorder in CKD." (PMID 34206780, 2021). "Instead, bone loss is mostly from cortical bone in subjects with CKD mineral and bone disorder (CKD-MBD), and their iPTH, alkaline phosphatase, Klotho, sclerostin, and fetuin A levels are pronouncedly altered." (PMID 27398932, 2016).